SOX1 (SRY-box transcription factor 1)
Diseases named in the same sentence as SOX1 in open-access papers (continued):
Sharing a sentence is not in itself a finding about the gene and the disease.
liver cancer (5 papers, 2014 to 2021). An epithelial or non-epithelial malignant neoplasm that arises from the liver. "For instance, SOX1 methylation is associated with liver cancer, and SOX1 promoter methylation level is significantly higher in patients with high TNM stage (stages III and IV) than in those with low TNM stage." (PMID 32849763, 2020). "The SOX1 methylation level is significantly higher in liver cancer patients with large tumor size (≥5 cm) than in those with small tumor size (<3 cm)." (PMID 32849763, 2020). "Previous reports showed that SOX1 acted as a tumor suppressor by interacting with β-catenin in cervical and liver cancers." (PMID 25427424, 2014). "Previous studies have demonstrated that SOX1 plays an essential role in liver cancer progression." (PMID 33531993, 2021).
paraneoplastic cerebellar degeneration (5 papers, 2013 to 2025). A rare, immune-mediated disorder characterized by cerebellar degeneration due to the presence of an often undetected malignancy (usually carcinoma or lymphoma) in an anatomic site other than the cerebellum. "Other neurological syndromes associated with anti-SOX1 antibodies have also been reported, including chronic axonal polyneuropathy, paraneoplastic limbic encephalitis and paraneoplastic cerebellar degeneration; however, MND or ALS is being reported for the first time." (PMID 36009116, 2022).
autoimmune disease (4 papers, 2022 to 2025). A disorder resulting from loss of function or tissue destruction of an organ or multiple organs, arising from humoral or cellular immune responses of the individual to their own tissue constituents. "Positive for paraneoplastic Yo antibody and SOX1 antibody; family history of autoimmune diseases." (PMID 41425549, 2025).
neuropathies (4 papers, 2019 to 2023). "SOX1 antibodies were found less frequently in patients with neuropathies (5/32, 16%), most often with associated SCLC and anti-Hu antibodies, although a similar number (4/22, 18%) had no underlying tumour." (PMID 30445363, 2019). "In this study we assessed the specificity and sensitivity of a commercial line blot test for SOX1 autoantibodies in a large series of patients with several types of neuropathies or PNS." (PMID 31031763, 2019). "Fifteen patients (1.0%) showed anti-SOX1 reactivity and nine of them had neuropathies." (PMID 31031763, 2019).
cervical intraepithelial neoplasia (3 papers, 2020 to 2024). "In a study identifying DNA methylation markers for the detection of high‐grade cervical intraepithelial neoplasia, the SOX1/ZSCAN1 panel (84%, 167/200) had a higher sensitivity and specificity compared to the others." (PMID 34056873, 2021). "The differences in the methylation statuses of three genes, PAX1, SOX1, and ZNF582, were evident between normal control samples and cervical intraepithelial neoplasm (CIN) I–III as well as SCC samples." (PMID 33003642, 2020).
colorectal cancer (3 papers, 2020 to 2025). A primary or metastatic malignant neoplasm that affects the colon or rectum. "Moreover, we noted that patients who experienced “new neoplasm event post initial therapy” in head and neck squamous cell carcinoma (HNSC), colorectal cancer, and tenosynovial giant cell tumor had elevated SOX1 expression in their original tumors." (PMID 37369660, 2023). "We also found that LMX1A, in combination with NKX6.1, SOX1, and ZNF177, could serve as a stage-independent prognostic marker in colorectal cancer." (PMID 32751497, 2020).
glioblastoma (3 papers, 2011 to 2023). The most malignant astrocytic tumor (WHO grade IV). "Moreover, we reveal that SOX1 is overexpressed in a subset of glioblastoma human biopsies and that its high levels are associated with shorter overall patient survival." (PMID 28425506, 2017). "The analysis of the TCGA database showed that SOX1 expression was low in most cancer types, except for glioblastoma tissues." (PMID 37369660, 2023). "Together, these results show that SOX1 expression is elevated in a subset of glioblastoma samples and its expression is a prognostic biomarker." (PMID 28425506, 2017). "Taken together, our data pointed out to a previously unappreciated role for SOX1 as a central player to glioblastoma biology, prognosis, and therapy." (PMID 28425506, 2017). "The analysis of SOX1 expression at mRNA level in a cohort of glioblastoma patients from Donostia Hospital indicated that SOX1 expression was slightly up-regulated in around 60% of tumor tissues compared to levels in healthy human brain samples." (PMID 28425506, 2017). "To further study this putative correlation between SOX2 and SOX1, we moved to clinical biopsies, analyzing the expression of those transcription factors in the Donostia Hospital cohort of human glioblastoma samples." (PMID 28425506, 2017). "In this work, we have identified that SOX1 displays oncogenic activity in glioblastoma by using several different approaches." (PMID 28425506, 2017). "Prior to this study, little was known about the impact of SOX1 in glioblastoma and in the maintenance of the GSC population." (PMID 28425506, 2017). "At the cellular level, SOX1 expression is elevated in patient-derived GSCs and it is also higher in oncosphere culture compared to differentiation conditions in conventional glioblastoma cell lines." (PMID 28425506, 2017). "Next, we investigated SOX1 levels in a small glioblastoma cohort derived from Donostia Hospital." (PMID 28425506, 2017). "In this study, we explore this hypothesis finding that SOX1 is overexpressed in a subset of glioblastomas which present overall shorter patient survival." (PMID 28425506, 2017). "Therefore, the oncogenic functions of SOX1 in glioblastoma seem to be β-catenin independent." (PMID 28425506, 2017). "In glioblastoma, however, we have not detected any remarkable effects of SOX1 silencing on difference in the expression of β-catenin and its downstream target MYC at a cellular level in vitro, in tumors in vivo, as well as in clinical biopsies." (PMID 28425506, 2017). "However, although we could detect a similar overlap in the expression pattern of Sox2, Oct4 and Nanog in ES cell-derived teratomas as in glioblastomas, teratoma cells did not express pluripotent stem cell markers in combination with NSC proteins such as Sox1." (PMID 21483788, 2011).
non-small cell lung carcinoma (3 papers, 2016 to 2025). A group of at least three distinct histological types of lung cancer, including non-small cell squamous cell carcinoma, adenocarcinoma, and large cell carcinoma. "SOX1 methylation, at least in part, is responsible for cisplatin resistance in human non-small cell lung cancer (NSCLC)." (PMID 27738327, 2016). "Taken together, these results showed that SOX1 is frequently downregulated by promoter hypermethylation in non-small-cell lung cancer, which may lead to aberrant activation of HES1." (PMID 37190139, 2023). "DNA methylation changes, especially hypermethylation of SOX1 and HOXA9, may serve as biomarkers for diagnosis and prognosis in non-small cell lung carcinoma (NSCLC)." (PMID 40699796, 2025).
prostate carcinoma (3 papers, 2010 to 2020). A carcinoma that arises from epithelial cells of the prostate gland. "Using the available online expression databases in Oncomine, it was determined that Sox1 plays a significant role in prostate cancer progression and metastasis." (PMID 20929579, 2010). "Overall, we demonstrate that SOX1 is an epigenetically regulated target involved in the progression of prostate cancer, and is involved in signaling via the STAT3 pathway." (PMID 20929579, 2010). "Overall, our data demonstrates that Sox1 is methylated in two prostate cancer cell lines, LNCaP and DU145, and two short-term primary prostate cancer cultures, PCSC1 and PCSC2, yet not methylated in the invasive compartment of these cells." (PMID 20929579, 2010). "However, the Oncomine and GEO data further support the observation that expression of both Sox1 and Stat3 are key genes regulating the progression of prostate cancer." (PMID 20929579, 2010). "Finally, using Oncomine, it was determined that more aggressive metastatic prostate cancers in humans also have higher levels of both Stat3 and Sox1." (PMID 20929579, 2010). "Finally, both Sox1 and Stat3 were found to have increased expression in relation to the progression of prostate cancer in humans." (PMID 20929579, 2010). "Thus, in our model SOX1 plays a critical role in regulating invasive prostate cancer cells." (PMID 20929579, 2010). "Additionally, the SOX1 gene interferes with the STAT3 signaling pathway and regulates prostate cancer stem cell invasion." (PMID 32675943, 2020). "Additional analysis using the GEO database determined that both Sox1 and Stat3 are expressed at higher levels in metastatic prostate cancer tissues and not Bmx." (PMID 20929579, 2010).
adenosquamous carcinoma (2 papers, 2013 to 2023). A carcinoma composed of malignant glandular cells and malignant squamous cells. "The co-methylation of SIX6 and SOX1, or the co-methyaltion of SIX6, RARB and SOX1 was associated with adenosquamous carcinoma (ADC), and the co-methylation of BCL2, RARB and SIX6 was associated with smoking." (PMID 23599765, 2013).
autoimmune encephalitis (2 papers, 2021 to 2025). Inflammation of the brain secondary to an immune response triggered by the body itself. "There were three or fewer cases of autoimmune encephalitis with antibodies directed against Caspr2, DPPX, GABABR, IgLON5, GFAP, and SOX1." (PMID 33692738, 2021). "Represented in smaller but still significant numbers were other subgroups of autoimmune encephalitis with other antigenic targets including glycine receptor, LGi1, Caspr2, DPPX, GABA-B, IgLON5, GFAP, and SOX1." (PMID 33692738, 2021). "Many of the autoimmune encephalitis subgroups (anti-DPPX, anti-GABABR anti-IgLON5, anti-GFAP, and anti-SOX1) had an antibody present in both serum and CSF in 100% of cases." (PMID 33692738, 2021).
cataract (2 papers, 2016 to 2017). Partial or complete opacity of the crystalline lens of one or both eyes that decreases visual acuity and eventually results in blindness. "Several genes that cause congenital cataract in mice also contribute to human cataracts, including Cryg, Connexin, Foxe3 and Sox1." (PMID 28135291, 2017). "Since the cataract symptoms of Sox1-Cre+; Rest2lox/2lox mice starts just after birth and obvious lens opacification is detected as early as one week after birth, the Rest CKO mouse is an uncommon cataract model." (PMID 27631609, 2016).
cerebellar degeneration (2 papers, 2021 to 2025). Degeneration of the cerebellum. "Both anti-Hu and anti-SOX1 antibodies have been associated with cerebellar degeneration." (PMID 41542009, 2025).
cholangiocarcinoma (2 papers, 2021 to 2023). A carcinoma that arises from the intrahepatic biliary tree (intrahepatic cholangiocarcinoma) or from the junction, or adjacent to the junction, of the right and left hepatic ducts (hilar cholangiocarcinoma). "To further explore the mechanisms of SOX1 in CCA, we detected the expression of two key proteins that interact with SOX1 (HES1, PROX1) and the signaling pathways related to cholangiocarcinoma (AKT, JNK, P38, ERK) by Western blot." (PMID 34876142, 2021). "However, the expression and role of SOX1 in cholangiocarcinoma (CCA) is not well characterized." (PMID 34876142, 2021).
colon cancer (2 papers, 2019 to 2021). "In the two most recent reports, SOX1 hypermethylation was also identified in colon cancer and CRC." (PMID 31547144, 2019).
Encephalopathy (2 papers, 2021). Encephalopathy is a term that means brain disease, damage, or malfunction. "Identification of other autoantibodies co-expressed with CRMP5 is important as peripheral neuropathy has also been associated with Hu and Sox1 antibodies and encephalopathy with Ri antibodies." (PMID 34630302, 2021). "Psychiatric symptoms, seizure, cognitive symptoms and encephalopathy were common presentations across the anti-LGi1, anti-Caspr2, anti-GABABR and anti-SOX1 subgroups." (PMID 33692738, 2021).
endometrial cancer (2 papers, 2012 to 2021). Primary or metastatic malignant neoplasm involving the endometrium (mucous membrane that lines the endometrial cavity). "Epigenetic repression of miR-129 also leads to over-expression of the SOX1 oncogene in gastric and endometrial cancer." (PMID 22438871, 2012).
epilepsy (2 papers, 2013 to 2017). A brain disorder characterized by episodes of abnormally increased neuronal discharge resulting in transient episodes of sensory or motor neurological dysfunction, or psychic dysfunction. "Sox1 expression is restricted to neuroectoderm in the mouse embryo and although Sox1-deficient mice are viable, they exhibit lens defects and suffer from spontaneous epilepsy seizures associated with abnormal forebrain development and olfactory cortex hyper-excitability." (PMID 23573229, 2013).
lung squamous cell carcinoma (2 papers, 2023 to 2025). "In squamous cell lung cancer, hypermethylation in genes SOX1 (p = 0.05) and HOXA9 (p = 0.01) is more frequent than in other histological types of NSCLC." (PMID 40699796, 2025).
medulloblastoma (2 papers, 2022 to 2023). A malignant, invasive embryonal neoplasm arising from the cerebellum. "In addition, ATOH1, GLI2, and SOX1 protein levels were significantly reduced in SI-CSC medulloblastomas but not in SD-CSC medulloblastomas that were resistant to LDE225." (PMID 36688010, 2022).
polyneuropathies (2 papers, 2019 to 2021). "Recent studies using immunoblot or ELISA suggested that SOX1 autoantibodies can occur in serum of patients with idiopathic polyneuropathies questioning the value of SOX1 autoantibodies as biomarkers of PNS associated with SCLC." (PMID 31031763, 2019). "All 139 sera from patients with polyneuropathies were SOX1 autoantibody-negative by the commercial line blot and SOX1 CBA." (PMID 31031763, 2019). "Overall, 210 patients were included in the study, 139 patients with polyneuropathies without SCLC, and 71 with disorders associated with SOX1 autoantibodies detected with the in-house CBA." (PMID 31031763, 2019). "None of the patients with polyneuropathies had SOX1 autoantibodies by either line blot or CBA (specificity of the immunoblot: 100%; 95%C.I.: 97.8–100)." (PMID 31031763, 2019). "We were unable to confirm previous findings of SOX1 antibodies in patients with non-paraneoplastic polyneuropathies." (PMID 31031763, 2019).
schizophrenia (2 papers, 2017 to 2025). A major psychotic disorder characterized by abnormalities in the perception or expression of reality. "About half of them has been previously associated with schizophrenia in humans, such as Olig1, Fgfr1, Gpr17, Gna12, Abca2, Sox1, Dpm2, and, as a locus for de novo mutations, Rab2a." (PMID 39825014, 2025). "An RNA sequencing analysis of the PFC suggested a dysregulation of numerous schizophrenia related genes including Olig1, Fgfr1, Gpr17, Gna12, Abca2, Sox1, Dpm2, and Rab2a in the rat model of psychosis." (PMID 39825014, 2025).
squamous cell carcinoma (2 papers, 2013 to 2025). A carcinoma arising from squamous epithelial cells. "Our analysis has revealed that histology, specifically squamous cell carcinoma, is significantly associated with the hypermethylation of both SOX1 and HOXA9." (PMID 40699796, 2025). "The co-methylation of SIX6, RARB and SOX1 occurred less frequently in adenocarcinoma (ADC) than in squamous cell carcinoma (OR, 0.45; 95% CI, 0.25–0.76)." (PMID 23599765, 2013). "We found that the co-methylation of SIX6 and SOX1 correlated with squamous cell carcinoma (SCC), while the methylation of neither of them individually demonstrated an association with SCC, which may imply that the methylation of these two genes had a superimposed effect on the development of SCC." (PMID 23599765, 2013).
teratoma (2 papers, 2011 to 2020). A non-seminomatous germ cell tumor characterized by the presence of various tissues which correspond to the different germinal layers (endoderm, mesoderm, and ectoderm). "To confirm the findings on PAX6 and SOX1, we performed immunostaining on cryostat sections from the teratomas." (PMID 32587369, 2020).
thymoma (2 papers, 2020 to 2024). A neoplasm arising from the epithelial cells of the thymus. "First, AE patients frequently have some particular tumors, which might be associated with multiple anti-neuronal antibodies such as GABABR, Hu, SOX1, and CV2 antibodies in SCLC, or LGI1 and AMPAR antibodies in thymoma." (PMID 38163879, 2024).
ZIKV infection (2 papers, 2022 to 2024). "Our results indicated that ZIKV infection did not affect SOX1 or SOX2 patterns." (PMID 35714598, 2022).
Anophthalmia (1 paper, 2023). Absence of the globe or eyeball. "We analyzed the expression of PAX6, PAX2, and SOX1 in microphthalmia mutants because structures expressing these proteins are missing in animals with anophthalmia, which we also see in our mutants." (PMID 37863656, 2023).
Anxiety (1 paper, 2019). Intense feelings of nervousness, tension, or panic often arise in response to interpersonal stresses. "Sox1 KO homozygotes display seizures beginning at late juvenile stages (age 4-6 weeks), and show evidence of freezing as well as other anxiety-related behaviors – all suggestive of phenotypes already noted for 16GsoT/T mice." (PMID 31554716, 2019).
autonomic neuropathy (1 paper, 2023). An inherited or acquired peripheral neuropathy affecting the autonomic nervous system. "Thyroid cancer can cause anti-SOX1 abs-associated PNS with only autonomic neuropathy." (PMID 37083806, 2023).
brain tumors (1 paper, 2017). "We analyzed the expression of SOX1 transcription factor in human clinical biopsies from brain tumors." (PMID 28425506, 2017).
cervical neoplasm (1 paper, 2015). "Combined parallel testing using Pap smears and PAX1 or SOX1 methylation tests may provide better performance than a combination of Pap smears with HPV-testing in detection of cervical neoplasm." (PMID 25985991, 2015). "In this study, we analyzed the concordance and clinical performance of DNA methylation biomarker (PAX1, SOX1, and ZNF582) detection in self-collected vaginal samples and physician-collected cervical samples for the identification of cervical neoplasm." (PMID 25985991, 2015). "The clinical performance of PAX1, SOX1, and ZNF582 as biomarkers of cervical neoplasm has been validated in multi-center clinical trials; therefore, analysis of changes in the methylation status of these genes could be applied for self-collected vaginal samples." (PMID 25985991, 2015).
colon adenocarcinoma (1 paper, 2019). "Moreover, the correlation analysis of the differential methylation and expression levels of LMX1A, SOX1, ZNF177 and NKX6.1 in colon adenocarcinoma patients was based on data derived from the MethHC database." (PMID 31547144, 2019).
Crohn disease (1 paper, 2022). A gastrointestinal disorder characterized by chronic inflammation involving all layers of the intestinal wall, noncaseating granulomas affecting the intestinal wall and regional lymph nodes, and transmural fibrosis. "In this report, we describe the interesting case of a patient with serum anti-SOX-1 antibodies and Crohn’s Disease (CD) with ensuing neurological symptoms." (PMID 36324062, 2022). "The patient had been suffering from Crohn’s Disease (CD) for approximately 20 years; she turned out positive for serum anti-SOX1 autoantibodies, in the absence of any underlying neoplastic disease." (PMID 36324062, 2022).
diabetes (1 paper, 2019). "Consistent with our previous findings, TuJ1-expressing neurons were absent, whereas Sox1 expression was enhanced in the E8.75 neuroepithelia from wild-type embryos exposed to maternal diabetes." (PMID 30655546, 2019).